STK11 (serine/threonine kinase 11)
Diseases named in the same sentence as STK11 in open-access papers (continued):
Sharing a sentence is not in itself a finding about the gene and the disease.
Peutz-Jeghers syndrome (229 papers, 1999 to 2025). "Genetic alterations to serine-threonine kinase 11 (STK11) have been implicated in Peutz-Jeghers syndrome and tumorigenesis." (PMID 39735555, 2025). "Peutz-Jeghers syndrome (PJS) is an autosomal dominant disorder caused by germline mutations in the tumor suppressor gene STK11." (PMID 40989965, 2025). "STK11/LKB1 is a tumor suppressor that regulates the mTOR pathway and is associated with Peutz-Jeghers syndrome in humans, where gastric polyps and increased cancer risk are observed." (PMID 40673273, 2025). "STK11 germ line mutations in humans are the cause of Peutz-Jeghers syndrome, a genetic disorder that raises the risk of hamartomas and cancer at various locations such as breast, gastrointestinal and gynecological cancers." (PMID 40171220, 2025). "The patient with the STK11 mutation later developed adrenocortical carcinoma, followed by a diagnosis of Peutz-Jeghers syndrome 11 years later." (PMID 40340749, 2025). "Since genetic screens identified STK11 mutations in Peutz-Jeghers Syndrome, STK11 mutants have been implicated in tumourigenesis labelling it as a tumour suppressor." (PMID 38844908, 2024). "Peutz-Jeghers syndrome is a rare, autosomal dominant inherited disorder caused by mutations in the STK11 tumor suppressor gene (also known as LKB1)." (PMID 37722995, 2024). "With the following specific exceptions: individuals with Peutz-Jeghers syndrome (STK11 mutation) from 35 years of age, FAMMM (CDKN2A mutation) from 40 years of age and Hereditary pancreatitis (PRSS1 mutation) from 40 years of age." (PMID 38753287, 2024). "The LKB1/STK11 gene encodes a serine/threonine protein kinase, and its mutation causes Peutz-Jeghers syndrome." (PMID 37591827, 2023). "STK11 is a serine and threonine kinase and a tumor suppressor gene, its germline inactivating mutation is associated with Peutz-Jeghers syndrome." (PMID 37345003, 2023). "Individuals with Peutz-Jeghers syndrome, associated with mutations inactivating the STK11 tumor suppressor gene, are at high risk for pancreatic cancer." (PMID 37452870, 2023). "Germline mutations in Serine/Threonine Kinase 11 (STK11) are considered a major cause of Peutz-Jeghers syndrome." (PMID 37470859, 2023). "Peutz-Jeghers syndrome is a rare autosomal dominant genetic disease caused by mutations in the STK11 gene." (PMID 34926254, 2021). "Heterozygous, pathogenic germline variants in the tumour suppressor gene STK11 are associated with the autosomal dominant disorder Peutz-Jeghers syndrome (PJS)." (PMID 34771713, 2021). "STK11 (Liver kinase 1, LKB1) was first identified as a tumor suppressor gene through its association with Peutz-Jeghers Syndrome." (PMID 34930302, 2021). "ClinVar is a repository for germline variants, and reports STK11 germline variants in the context of Peutz-Jeghers Syndrome." (PMID 34849607, 2021). "Inactivating mutations of the tumor suppressor serine-threonine kinase 11/liver kinase B1 (STK11/LKB1), which can play a role in the regulation of the UV-induced DNA damage response in mice skin, underlie Peutz-Jeghers syndrome." (PMID 33918445, 2021). "Heterozygous germline STK11 LoF variants are pathognomonic for Peutz-Jeghers syndrome, an autosomal dominant heritable cancer predisposition syndrome characterized by melanocytic macules of the oral mucosa and gastrointestinal hamartomas." (PMID 34849607, 2021). "It has been recently shown that STK11 is a tumor suppressor gene associated with Peutz-Jeghers syndrome, which is a multiple-cancer susceptible disease characterized by inactivation of LKB1." (PMID 32911741, 2020). "STK11 kinase activity elimination is associated with the Peutz-Jeghers syndrome and an elevated cancer risk." (PMID 32373524, 2020).
Peutz-Jeghers syndrome (continued). "Peutz-Jeghers syndrome (PJS) is a rare autosomal dominant inherited disease caused by a germline mutation in the STK11 gene." (PMID 32462036, 2020). "Peutz-Jeghers syndrome (PJS) is an autosomal dominant inherited disorder with germline mutation in serine/threonine kinase-11 (STK11) gene and characterized by intestinal hamartomatous polyps with skin melanocytes macules." (PMID 31845182, 2020). "These syndromes are characterized by mutations in STK11 (Peutz-Jeghers syndrome, PJS) or PTEN (PTEN hamartoma tumor syndrome, PHTS), which encode for FOXO3 upstream regulators." (PMID 31303978, 2019). "For example, pathogenic variants in STK11 are diagnostic of Peutz-Jeghers syndrome, which is associated with a high risk of breast, colorectal, endometrial, pancreatic, gastric, ovarian, and other cancers." (PMID 31623605, 2019). "Peutz-Jeghers Syndrome (PJS) is a hereditary cancer predisposing syndrome caused by autosomal dominant mutations in the serine/threonine kinase 11 (STK11) gene and is associated with decreased life expectancy." (PMID 29720104, 2018). "Consistent with this, mutations in the polarity-regulating protein kinase LKB1/STK11 have been identified in individuals with Peutz-Jeghers Syndrome (PJS), an autosomal dominant disease that predisposes patients to various types of cancer." (PMID 29907081, 2018). "Liver kinase B1 (LKB1) functions as a tumor suppressor encoded by STK11, a gene that mutated in Peutz-Jeghers syndrome and in sporadic cancers." (PMID 27705915, 2016). "Sirolimus has shown promising effects in patients with inactivating mutations in TSC1, TSC2 and STK11 in hamartoma syndromes such as tuberous sclerosis complex and Peutz-Jeghers Syndrome." (PMID 26859683, 2016). "Several women in the maternal lineage have comorbidities typically associated with Peutz Jeghers Syndrome, a rare autosomal-dominant disease caused by mutations in the serine-threonine-kinase 11 (STK11) gene, which encodes liver kinase B1." (PMID 25694554, 2015). "Peutz-Jeghers syndrome is an autosomal-dominant disorder that arises as a consequence of mutations in the serine/threonine kinase 11 (STK11) gene that encodes LKB1." (PMID 26236179, 2015). "Five hereditary syndromes are associated with an increased risk of PDAC; 1/ The Peutz-Jeghers syndrome caused by germline mutations in the STK11/LKB1." (PMID 26498142, 2015). "LKB-1/STK11 is mutated in the Peutz-Jegher syndrome, characterized by predisposition to GI neoplasms, including PDAC." (PMID 25295009, 2014). "Analysis of the STK11 gene showed a missense mutation leading to the amino acid change E199D in the kinase domain, confirming the diagnosis of Peutz-Jeghers syndrome." (PMID 24932598, 2014). "STK11 has been associated with Peutz-Jeghers syndrome (PJS), a condition that enhances the formation of gastric adenomatous polyps and hepatocellular carcinoma." (PMID 25259881, 2014). "Germline mutations in LKB1 (STK11) are associated with the Peutz-Jeghers syndrome (PJS), which includes aberrant mucocutaneous pigmentation, and somatic LKB1 mutations occur in 10% of cutaneous melanoma." (PMID 24743024, 2014). "Peutz - Jeghers syndrome is preconditioned by the manifestation of mutations in the STK11 (OMIM*602216 Serine/Threonine Protein Kinase 11) gene, located in the short arm of chromosome 19, in the 13.3 region." (PMID 23724922, 2013). "As a tumor suppressor gene, STK11/LKB1 abnormality is the underlying mechanism for Peutz-Jeghers syndrome (PJS)." (PMID 24278753, 2012).
Peutz-Jeghers syndrome (continued). "Peutz-Jeghers Syndrome patients have autosomal dominant mutations in the LKB1/STK11 gene and are prone to developing cancer, predominantly in the intestinal tract but also in other tissues, including the reproductive tracts and gonads." (PMID 22916036, 2012). "Peutz-Jeghers syndrome is caused by mutations in the STK11/LKB1 gene, a serine threonine kinase involved in a large number of cellular functions, from control of cell polarity to metabolism." (PMID 21512581, 2011). "Germline mutations in the LKB1 (STK11) gene (chromosome sub-band 19p13.3) cause characteristic hamartomas and pigmentation to develop in patients with Peutz-Jeghers syndrome." (PMID 10389980, 1999). "STK11 gene mutations are associated with Peutz-Jeghers syndrome (PJS)." (PMID 39955067, 2025). "The tumor suppressor gene STK11 encoding Serine/Threonine Kinase 11 (STK11) is associated with Peutz-Jeghers Syndrome (PJS), a heritable gastrointestinal disease that increases lifetime cancer risk, and with somatic variation that contributes to ~30% of lung and 20% of cervical cancers." (PMID 40791513, 2025). "Peutz-Jeghers syndrome (PJS) is caused by a PGV in the STK11 gene." (PMID 39932614, 2025). "Liver kinase B1 (LKB1), a tumor suppressor encoded by serine/threonine kinase 11 (Stk11), was first associated with Peutz-Jeghers syndrome and was involved in the control of embryonic development, tissue homeostasis, stem cell function, energy metabolism, and apoptosis." (PMID 36499390, 2022). "If a patient presents clinically as concerning for Peutz-Jeghers Syndrome, and a germline missense variant is identified in STK11, then the variant may be flagged as likely pathogenic." (PMID 34849607, 2021). "Germinal heterozygous mutations in the serine/threonine kinase 11 (STK11) gene were first identified as the causal mutation of the Peutz-Jeghers Syndrome, an autosomal dominant condition characterized by multiple hamartomatous polyps in the gastrointestinal tract and an increased cancer risk." (PMID 34831355, 2021). "As a result, several patients may have had undiagnosed multiple PJPs or STK11/LKB1 germline mutations; thus, true Peutz-Jeghers syndrome may have been misdiagnosed as solitary PJP." (PMID 31582972, 2019). "The Liver Kinase B1 (LKB1, also known as STK11) is a tumor suppressor gene encoding a ubiquitously expressed and evolutionarily conserved serine threonine kinase, originally associated with the inherited cancer disorder Peutz-Jeghers Syndrome." (PMID 31781355, 2019). "Peutz-Jeghers syndrome (PJS) is caused by mutations in serine/threonine kinase 11 (STK11) gene." (PMID 30092773, 2018). "Germline mutations of the Liver Kinase b1 (LKB1/STK11) tumor suppressor gene have been linked to Peutz-Jeghers Syndrome (PJS), an autosomal-dominant, cancer-prone disorder in which patients develop neoplasms in several organs, including the oviduct, ovary, and cervix." (PMID 22916036, 2012). "Peutz-Jeghers syndrome (PJS) is an autosomal dominant disorder caused by germline mutations in the STK11 tumor suppressor gene." (PMID 40989965, 2025). "Peutz-Jeghers syndrome (PJS) is a rare hereditary disorder characterized by gastrointestinal hamartomatous polyps, due to mutation of the STK11/LKB1 gene located on chromosome 19p." (PMID 39098175, 2024). "Serine/threonine kinase gene (STK11) functions as a tumor suppressor gene, and its mutation can lead to Peutz-Jeghers syndrome (PJS)." (PMID 38970069, 2024). "Peutz-Jeghers syndrome (PJS) is a rare autosomal dominant inherited disorder caused by germline mutations in the serine-threonine kinase 11 (STK11) tumor suppressor gene." (PMID 36874343, 2023).
Peutz-Jeghers syndrome (continued). "Peutz-Jeghers Syndrome (PJS) is an autosomal dominant disease resulting from heterozygous pathologic variants in STK11 possessing nearly 100% penetrance." (PMID 35685436, 2022). "Similarly, those with germline inactivation of the APC gene, associated with familial adenomatous polyposis (FAP), have a 4.5% lifetime risk of developing SBA, while those with an inherited STK11 mutation, resulting in Peutz-Jeghers syndrome (PJS), have a relative risk of 520 for developing SBA." (PMID 35267592, 2022). "Peutz-Jeghers syndrome (PJS) is a rare autosomal dominant inherited disease caused by mutations in the Serine-Threonine Kinase 11 (STK11) gene." (PMID 36550395, 2022). "Indeed, the role of genes other than BRCA in cancer susceptibility inheritance is well established, and PC is part of the clinical spectrum in several syndromes (e.g. Lynch syndrome from mismatch repair (MMR) gene mutations, Peutz-Jeghers syndrome from STK11 mutations)." (PMID 34034685, 2021). "Heterozygous germline mutations in Stk11 lead to the development of Peutz-Jeghers syndrome (PJS), an autosomal dominant disease with hamartomatous polyp formation in the gastrointestinal tract." (PMID 33236987, 2020). "The serine-threonine kinase LKB1 (STK11) is mutated in the tumor predisposition Peutz-Jeghers syndrome (PJS), an inherited human disorder characterized by skin pigmentation and hamartomatous polyps of the GI tract." (PMID 31798532, 2019). "Peutz-Jeghers syndrome (PJS) is caused by mutations in the tumor suppressor gene, STK11, and is characterized by gastrointestinal hamartomas, melanin spots on the lips and the extremities, and an increased risk of developing cancer." (PMID 29141581, 2017). "Tumor suppressor gene STK11 (also named LKB1) is located on chromosome 19p13.3, and germline mutations of it are dominant in Peutz-Jeghers Syndrome (PJS) patients." (PMID 27077911, 2016). "Liver kinase B1 (LKB1; also known as STK11) is a serine/threonine kinase and tumour suppressor that is mutated in Peutz-Jeghers syndrome (PJS), a premalignant syndrome associated with the development of gastrointestinal polyps." (PMID 25190708, 2014). "Peutz-Jeghers syndrome (PJS) is characterized by intestinal polyposis, mucocutaneous pigmentation and an increased cancer risk, usually caused by mutations of the STK11 gene." (PMID 24260271, 2013). "Peutz-Jeghers syndrome (PJS) is an autosomal dominant syndrome associated with loss of STK11/LKB1 gene function and is characterized by hamartomatous polyps in the gastrointestinal tract and pigmented skin lesions on the lips, oral mucosa, and digits." (PMID 22312493, 2011). "In Group 2, genetic testing confirmed Peutz-Jeghers Syndrome in a young girl who had a large deletion in the STK11 gene." (PMID 40554495, 2025). "The STK11 gene is associated with Peutz-Jeghers syndrome when present as a germline mutation, which confers an increased risk of CRC; however, STK11 mutations are exceptionally rare in sporadic CRC (<1%)." (PMID 41230344, 2025). "When a genetic association is present, SCTs are most commonly linked to Peutz-Jeghers syndrome, which is caused by mutations in the STK11/LKB1 gene." (PMID 40406374, 2025). "Genetic screening patients diagnosed with Peutz-Jeghers syndrome (PJS) first linked serine-threonine kinase 11 (STK11), hereafter liver kinase B1 (LKB1) mutations to disease." (PMID 39735555, 2025). "STK11, PTEN, and ATM are implicated in syndromes like Peutz-Jeghers syndrome (PJS), Cowden syndrome (CS), and Ataxia–Telangiectasia (Louis-Bar Syndrome) respectively." (PMID 39390525, 2024). "A multi-disciplinary team discussion was held regarding this case and genetic testing for STK11/LKB1 gene to exclude Peutz-Jeghers syndrome was recommended." (PMID 39119533, 2024). "STK11 is a significant disease gene due to its involvement in both the rare genetic disorder, Peutz-Jeghers Syndrome (PJS), and cancer." (PMID 39011112, 2024).
Peutz-Jeghers syndrome (continued). "STK11 adnexal tumour is a recently described female genital tract tumour, usually identified in a paratubal location, often associated with Peutz-Jeghers syndrome (PJS) and with STK11 gene alterations identified in most of the cases." (PMID 38376618, 2024). "Liver kinase B1 (LKB1), also known as serine threonine kinase 11 (STK11), is a tumor suppressor protein originally identified as the causative gene of Peutz-Jeghers syndrome (PJS), which is closely associated with the development of gastrointestinal polyps and cancer." (PMID 36077459, 2022). "Peutz-Jeghers syndrome (PJS) is a rare, autosomal dominant disorder caused by germline mutations of STK11/LKB1, with an increased risk of tumors at multiple sites." (PMID 36578081, 2022). "Within this locus, the most obvious candidate is STK11, a well-known tumor suppressor gene involved in Peutz-Jeghers syndrome." (PMID 35965534, 2022). "A mouse model of Peutz-Jeghers syndrome (PJS) with STK11/LKB1 inactivation showed a dramatic HIF-1α increase via the mTOR pathway." (PMID 34831355, 2021). "The serine/threonine-specific liver kinase B1 (LKB1), encoded by the STK11 gene, is a tumor suppressor, which is mutated in patients with the hereditary Peutz-Jeghers syndrome." (PMID 34193159, 2021). "Liver kinase B1 (LKB1) or serine/threonine kinase-11, a 436-amino acid chain protein with a molecular weight of 49 kDa, is associated with the development of Peutz-Jeghers syndrome (PJS)." (PMID 30696074, 2019). "Peutz-Jeghers syndrome (PJS) is a Mendelian disease, whose causative gene is STK11, mainly characterized by gastrointestinal polyposis and increased cancer risk." (PMID 31072341, 2019). "The presence of brown pigmentations and multiple gastrointestinal polyps alerted us to a possible diagnosis of Peutz-Jeghers syndrome and serine/threonine kinase 11 (STK11, also called LKB1) mutation was found positive in both the patient and his mother." (PMID 30040067, 2019). "Germline mutations in the LKB1/STK11 tumour suppressor gene cause Peutz-Jeghers Syndrome (PJS)." (PMID 30134550, 2018). "Among the 13 identified carriers, the STK11 carrier had a clinical diagnosis of Peutz-Jegher syndrome with multiple affected relatives, and 9 additional patients met criteria for HBOC or Lynch syndrome genetic testing." (PMID 29945567, 2018). "Liver Kinase b1 (LKB1/STK11)is a tumor suppressor responsible for the Peutz-Jeghers syndrome, an autosomal-dominant, cancer-prone disorder in which patients develop neoplasms in several organs, including the oviduct, ovary, and cervix." (PMID 26745759, 2016). "Liver kinase B1 (LKB1, STK11) is key regulatory protein of cellular metabolism that was originally identified in patients with Peutz-Jeghers syndrome (PJS), an autosomal dominant disease associated with LKB1 germline alterations." (PMID 26015068, 2015). "LKB1 (liver kinase B1, also known as STK11) is a serine/threonine kinase that was first identified as a tumor suppressor gene associated with Peutz-Jeghers syndrome." (PMID 25996931, 2015). "Germline mutations in the serine/threonine kinase gene (STK11/LKB1), a tumour-suppressor gene important for mediation of apoptosis and cell cycle regulation, cause Peutz-Jeghers syndrome." (PMID 23586058, 2013).